RNU2-64P (RNA, U2 small nuclear 64, pseudogene)
Gene: Small nuclear RNA gene on chromosome 3 (73,110,992 to 73,111,182, forward strand). Ensembl gene ENSG00000223247.
Homologues: Orthologues: chimpanzee U2 (99% identical), rat U2l3 (86% identical), rabbit U2 (62% identical), tropical clawed frog U2 (30% identical). Paralogues in human: U2 (87% identical), RNU2-14P (85% identical), RNU2-61P (85% identical), RNU2-32P (84% identical), RNU2-4P (84% identical), RNU2-59P (84% identical), RNU2-26P (83% identical), RNU2-2 (83% identical), RNU2-57P (83% identical), RNU2-23P (82% identical), RNU2-3P (82% identical), RNU2-48P (82% identical), and 66 more.